GFAP (glial fibrillary acidic protein)
Diseases named in the same sentence as GFAP in open-access papers (continued):
Sharing a sentence is not in itself a finding about the gene and the disease.
acute disseminated encephalomyelitis (9 papers, 2016 to 2025). Acute disseminated encephalomyelitis (ADEM) is a demyelinating disorder of the central nervous system. "Importantly, both astrocyte markers, particularly GFAP, are expressed at significantly higher levels than in MS (GFAP even several thousand times higher), acute disseminated encephalomyelitis (ADEM), spinal cord infarction or other neurological diseases." (PMID 26950113, 2016). "For example, targeted immunoassays support increased levels of Hp and GFAP in NMOSD with respect to all comparison cohorts studied, with the exception of acute disseminated encephalomyelitis (ADEM), by as much as 1000-fold." (PMID 32961928, 2020). "Additionally, a patient suspected of acute disseminated encephalomyelitis (PT-32) showed demyelination on brain biopsy but was negative for MOG, AQP4 and GFAP antibodies." (PMID 40342619, 2025).
bipolar disorder (9 papers, 2014 to 2026). A disorder of the brain that causes unusual shifts in mood, energy, activity levels and the ability to carry out day-to-day tasks. "We found that both are mildly elevated compared to healthy controls, with higher NfL associated with a longer duration of bipolar disorder, while GFAP was associated with a later age of onset." (PMID 40265626, 2025). "Plasma GFAP was significantly elevated in people with bipolar depression compared to healthy controls after adjusting for age, sex and weight (β = 0.21 [0.07, 0.35], p = 0.006)." (PMID 40265626, 2025). "In this study, we aimed to further investigate the bipolar depression group by analysing plasma GFAP concentrations and comparing them with healthy controls." (PMID 40265626, 2025). "Only one study investigated GFAP in a small number of people with bipolar disorder found that serum GFAP levels were similar to healthy controls." (PMID 40265626, 2025). "Plasma GFAP (β = 0.21 [0.07, 0.35], p = 0.006) and NfL (β = 0.06 [0.01, 0.10], p = 0.028) were elevated in people with bipolar depression." (PMID 40265626, 2025). "The raw mean ± SD of GFAP was 95.6 ± 49.3 pg/mL in bipolar depression and 75.5 ± 46.9 pg/mL in healthy controls." (PMID 40265626, 2025). "Given the evidence of astroglial pathology and neuronal dysfunction in bipolar disorder, and ongoing debates on neuroprogression, we investigated plasma NfL and GFAP levels in affected individuals." (PMID 40265626, 2025). "By extending on our previous work, we found that both plasma NfL and GFAP are elevated in people with bipolar depression compared to healthy controls." (PMID 40265626, 2025). "In conclusion, this is the largest study to date that has investigated plasma NfL and GFAP in people with bipolar disorder." (PMID 40265626, 2025). "Considering the broader literature, our finding suggests that the “neuroprogressive” pathology of bipolar disorder outpaces chronological age‐related brain changes, and this has a neuroinflammatory component given the elevated GFAP levels." (PMID 40265626, 2025). "We used bootstrapped general linear models (GLM) to compare plasma NfL and GFAP levels between people with bipolar depression (n = 120) and healthy controls (n = 96), adjusting for age, sex, and weight." (PMID 40265626, 2025). "Our finding of elevated GFAP levels in bipolar disorder suggests that neuroinflammation may be a component of this condition, especially in those with later onset of illness." (PMID 40265626, 2025). "Despite lithium's postulated neuroprotective role, it also did not have a significant effect on plasma NfL nor GFAP, though it may have been underpowered considering that plasma NfL and GFAP levels were only mildly elevated in people with bipolar disorder." (PMID 40265626, 2025). "Additional research involving cohorts in different phases of bipolar disorder (i.e., index episode, acute manic episode) is needed to validate whether the differences in NfL and GFAP are generalisable to the disorder or are episode dependent." (PMID 40265626, 2025). "Investigating NfL and GFAP in the blood of individuals with bipolar depression could provide valuable insights into the extent of neuronal pathology and astrocyte activation associated with the disorder, providing new avenues for therapeutic strategies." (PMID 40265626, 2025). "Our novel finding that plasma GFAP was elevated in bipolar depression suggests that there is increased activation of astrocytes, which has been linked with neuroinflammation, adding to the debated literature about the role of inflammation in bipolar disorder and the neuroprogression hypothesis." (PMID 40265626, 2025). "We found that the severity of depressive symptoms did not correlate with plasma NfL nor GFAP suggests that unipolar and bipolar depression may have different underlying neurobiological processes." (PMID 40265626, 2025).
bipolar disorder (continued). "However, GFAP did not correlate with peripheral interleukin‐6 (IL‐6) or total antioxidant capacity (TAC), suggesting that peripheral and CNS inflammation may contribute to the pathophysiology of bipolar disorder in distinct ways." (PMID 40265626, 2025).
brain inflammation (9 papers, 2017 to 2023). "The results showed that the intensity of GFAP labeling was higher in the DSS group, and astrocytes were substantially activated, indicating that DSS treatment caused severe brain inflammation." (PMID 37235662, 2023). "Systemic and brain inflammation were measured by plasma cytokine assay and glial fibrillary acidic protein (GFAP) staining." (PMID 35203995, 2022). "They found evidence of brain inflammation, documented by elevations of neurofilament light (NfL) and glial fibrillary acidic protein (GFAP) in a severity dependent manner, not only during acute disease but still persistent at follow-up 4 months later." (PMID 35264003, 2022). "GFAP is a commonly used marker for astrocytes, and it has been related to brain inflammation and to the proper functioning of the blood-brain barrier in health." (PMID 29138750, 2017). "In summary, our findings revealed that perinatal food restriction of the mother have clear effects in brain inflammation at early stages of postnatal life, increasing the number and reactivity of Iba-1-immunopositive cells and also increasing the number of GFAP-immunopositive cells." (PMID 30518432, 2018). "We observe that treatment with FeTPPS (30 mg/kg, i.p.)reduced: the state of brain inflammation and the tissue hurt (histological score), myeloperoxidase activity, nitric oxide production, glial fibrillary acidic protein (GFAP) and pro-inflammatory cytokines expression and apoptosis process." (PMID 28223911, 2017). "Despite the previously reported expression of MC1R in a human astrocyte cell line and suggested glial cell MC1R-mediated inhibition of TNF-α by α-MSH in a mouse model of brain inflammation, our double-labeling showed rare colocalization of MC1R and GFAP." (PMID 35197079, 2022). "Pediatric brain biopsy can diagnose SV-cPACNS and rule out other mimicking conditions, especially inflammatory brain diseases such as GFAP astrocytopathy." (PMID 36737749, 2023).
hemorrhage (9 papers, 2017 to 2023). Loss of blood from the vascular compartment to the exterior or into nonvascular body space as a result of rupture or severance of the blood vessels. "AQP2 was partly localized in astrocytes labeled with GFAP and upregulated simultaneously with GFAP in the collagenase-induced hemorrhage rat brain." (PMID 35386692, 2022). "GFAP (glial fibrillary acidic protein), another glial protein specific to astrocytes, is the best candidate to date for differentiating hemorrhage and ischemic stroke." (PMID 33633673, 2021). "In humans, serum or plasma GFAP levels can predict brain abnormalities including hemorrhage on computed tomography (CT) scans and magnetic resonance imaging (MRI)." (PMID 33678186, 2021). "Additional well-studied biomarkers, such as GFAP, might be considered in future studies to further distinguish LVO from hemorrhage." (PMID 38371304, 2023). "Moreover, GFAP levels were demonstrated to be positively correlated with hemorrhage volume and neurological deficit, as ICH patients suffering from larger and more severe hemorrhages were characterized by elevated GFAP levels." (PMID 36278689, 2022).
myoepithelioma (9 papers, 2008 to 2025). "Immunohistochemical expression of pan-cytokeratin (CKAE1/AE3), p63, anti-smooth muscle actin (ASMA) and glial fibrillary acidic protein (GFAP) supported the diagnosis of myoepithelial neoplasm." (PMID 33520519, 2020). "Immunohistochemical expression of CKAE1/AE3, p63, ASMA, S100 and GFAP favored the diagnosis of benign myoepithelioma." (PMID 26170201, 2015). "Immunohistochemical requirement for the diagnosis of myoepithelial tumors is the expression of S100, GFAP or ASMA in addition to cytokeratin stains." (PMID 26170201, 2015). "The combination of SMA, GFAP, S-100, and vimentin positive cells in these lesions aids in the diagnosis of malignant myoepithelioma." (PMID 23642050, 2013). "Additional immunohistochemical markers such as GFAP, which may be positive in myoepithelioma/myoepithelial carcinoma, and SMARCB1, which may show mosaic loss specifically in OFMT, are useful for such differential diagnosis." (PMID 40151688, 2025). "Moreover, soft-tissue myoepitheliomas are usually positive for S100 protein and/or GFAP, and many cases express calponin, whereas these markers were completely negative in our pleural tumor." (PMID 29625594, 2018). "Moreover, EMA, glial fibrillary acidic protein and a variety of myogenic markers are also expressed in myoepitheliomas." (PMID 21917131, 2011). "Almost all cases of myoepithelioma are strongly positive for Calponin, S-100 protein and the tumor cells also display varying degrees of immunoreactivity for cytokeratins, Glial fibrillary acidic protein (GFAP), myosin, actin, vimentin and carcinoembryonic antigen (CEA)." (PMID 18620583, 2008). "Myoepithelial tumors are characteristically positive for myoepithelial markers including vimentin, cytokeratin, SMA, S100 and GFAP." (PMID 23642050, 2013). "Absent staining for epithelial markers, S100, and GFAP ruled out myoepithelial neoplasm." (PMID 40705064, 2025).
astroblastoma (8 papers, 2007 to 2023). "Due to tumor localization, type of perivascular pseudorosettes, and abundant glial fibrillary acidic protein (GFAP)-positive eosinophilic epithelioid neoplastic astrocytes, it was subsequently considered to be consistent with an astroblastoma." (PMID 22011735, 2011). "Other tumors also traditionally called astroblastomas more highly express OLIG2, GFAP, ALDH1L1, and S100 β astrocyte genes and exhibit histomorphologic and patient demographic characteristics more closely matching original descriptions of astroblastoma." (PMID 36604386, 2023). "GFAP immunoreactivity was identified in the cytoplasm and fibrillary processes of tumors with EPN-like, astroblastoma-like features, whereas no immunopositivity or only a focal expression was detected in tumors with sarcoma-like and PXA-like features." (PMID 34389065, 2021).
autoimmune disease of the central nervous system (8 papers, 2018 to 2025). "In recent years anti-glial fibrillary acidic protein (anti-GFAP) antibodies have been associated with autoimmune central nervous system diseases that present with epileptic seizures." (PMID 40538658, 2025). "Autoimmune glial fibrillary acidic protein (GFAP) astrocytopathy is a rare autoimmune disease of the central nervous system that affects the meninges, brain, spinal cord, and optic nerves." (PMID 38996095, 2024). "Glial fibrillary acidic protein astrocytopathy (GFAP-A) is a rare autoimmune disease of the central nervous system that was newly reported in 2016." (PMID 35795195, 2022). "Autoimmune glial fibrillary acidic protein (GFAP) astrocytopathy is an autoimmune disease of the central nervous system characterized by positive GFAP autoantibody." (PMID 34646641, 2021). "Glial fibrillary acidic protein astrocytopathy is an immunotherapy-responsive autoimmune disease of the central nervous system with various clinical manifestations; among these, there are few reports about area postrema syndrome (APS)." (PMID 35002942, 2021). "Glial fibrillary acidic protein (GFAP) astrocytopathy, an autoimmune central nervous system disorder with a specific GFAP-IgG, often coexists with other antibodies." (PMID 29755396, 2018).
Down syndrome (8 papers, 2013 to 2025). "Another study in adults with Down syndrome showed that verbal fluency performance was negatively correlated with the established AD biomarkers, neurofilament light, and glial fibrillary acidic protein." (PMID 38463041, 2024). "In addition, Down syndrome astrocytes display increased glial fibrillary acidic protein (GFAP) and S100B expression and nitric oxide generation, indicating that they are in a reactive state." (PMID 25426477, 2014).
infarction (8 papers, 2018 to 2022). A localised pathological necrosis of tissue resulting from obstruction of the blood supply usually by a thrombus, an embolus, or vascular torsion. "Larger relative infarction size was associated with a higher increase in GFAP (ρ = 0.41; p = 0.009)." (PMID 36142218, 2022). "Along with a larger infarction size, patients with a GFAP increase also tended to have higher peak values of troponin T, creatine kinase, and lactate dehydrogenase, but these trends were not significant." (PMID 36142218, 2022). "Taken together, we here propose a differential increase in the glial biomarker GFAP in the first year after MI, which might relate to infarction size." (PMID 36142218, 2022). "Indeed, a higher relative infarction size early after MI was correlated with an increase in GFAP." (PMID 36142218, 2022). "When we compared patients with a GFAP increase to those without, relative infarction size was the only parameter, which was significantly different between groups." (PMID 36142218, 2022). "The results showed that cGLIS3 silencing did no further alter neurological severity score, cerebral infarct size, neuronal apoptosis, NeuN signaling, and GFAP signaling in sham-operation group." (PMID 33408783, 2021). "In the cortex, pERK1/2 and aquaporin 4 expressions increased significantly in the infarction area, while glial fibrillary acidic protein (GFAP) reduced significantly compared with the noninfarction side in brain cortex." (PMID 32985231, 2020).
inflammatory bowel disease (8 papers, 2016 to 2025). A spectrum of small and large bowel inflammatory diseases of unknown etiology. "GFAP level increases in inflammatory conditions such as neurological damage and inflammatory bowel disease (IBD)." (PMID 37886003, 2023). "Active gliosis has been observed in the gut of patients with inflammatory bowel disease and in vitro TFNα induced increase in GFAP level in EGC." (PMID 35024040, 2021). "Similarly, under inflammatory bowel disease (IBD) conditions, gliogenesis occurs within the EGC network and prominent alterations in the expression levels of GFAP as well." (PMID 26964064, 2016). "In the small intestine of patients with Crohn’s disease, a type of inflammatory bowel disease (IBD), SOX10, PLP1, and S100B transcripts were highly enriched in mucosal glia while GFAP was enriched in various non-glial cells including fibroblasts and immune cells." (PMID 40227232, 2025).
lymphoma (8 papers, 2009 to 2025). A malignant (clonal) proliferation of B- lymphocytes or T- lymphocytes which involves the lymph nodes, bone marrow and/or extranodal sites. "Immunohistochemistry staining showed positivity for NSE, synaptophysin, chromogranin A, CD56, S100 protein neurofilaments, calretinin, and glial fibrillary acidic protein and was negative for epithelial and lymphoma markers." (PMID 40821301, 2025).
pancreatic cancer (8 papers, 2016 to 2025). "Previous research demonstrated that pancreatic cancer cell supernatants under hypoxic conditions can induce GFAP activation in human SCs." (PMID 40148311, 2025). "IL-8 increased GFAP expression by SCs, which has also been highlighted in as a sign of activation in nerve injury and thyroid, head and neck, skin, colon, and pancreatic cancers." (PMID 40160208, 2025). "Pancreatic tumors strongly produced and secreted glucagon, suggesting that they derived from glucagon- and GFAP-positive islet cells." (PMID 27769070, 2016). "Moreover, LC3 expression was even stronger in nerves than in pancreatic cancer tissue and had the same position as GFAP-positive Schwann cells." (PMID 35109895, 2022). "In pancreatic cancer, α-SMA+ vimentin+ glial fibrillary acidic protein+ (GFAP), CAFs secret macrophage colony-stimulating factor 1 (M-CSF), IL-6, and CC-chemokine ligand 2 (CCL2) to promote monocyte recruitment encourage macrophage differentiation and M2 polarization." (PMID 31462327, 2019).
relapsing-remitting MS (8 papers, 2019 to 2026). "Serum neurofilament light chains (sNfL) and glial fibrillary acidic protein (sGFAP) associate respectively with acute inflammation and smoldering disease in relapsing-remitting multiple sclerosis (MS) patients." (PMID 41425552, 2025). "Furthermore, progressive MS is more strongly associated with increased cerebrospinal fluid GFAP levels compared to relapsing-remitting MS, suggesting that GFAP could serve as a useful marker for disease progression." (PMID 39565457, 2025).
synucleinopathies (8 papers, 2021 to 2025). "When combined with other biomarkers—such as neurofilament light chain, amyloid, tau, and glial fibrillary acidic protein—and applied to diverse biological samples, these assays can significantly improve the diagnostic precision for synucleinopathies." (PMID 39574205, 2024). "When we compared CSF-GFAP levels in different types of alpha-synucleinopathies, our obtained data indicated elevated GFAP levels in patients with MSA compared with PD (p < 0.05)." (PMID 34630068, 2021). "In the present report, α-synucleinopathy (α-synuclein), neurodegeneration (Neu-N), astrogliosis (GFAP), and microgliosis (Iba-1) were quantified, using specific markers and stereological methods." (PMID 33479244, 2021). "Emerging plasma biomarkers—such as GFAP and αSyn-SAA—as well as neuroimaging techniques, including MRI and FDG-PET, may aid in detecting additional pathologies implicated in disease progression, such as vascular brain injury, neuroinflammation, and α-synucleinopathy (Jack Jr." (PMID 40661287, 2025). "In this study, we analyzed the concentration of potential marker protein candidates, such as neurofilament light chain (NfL), glial fibrillary acidic protein (GFAP), a-Syn, and total tau (tau) in patients with different types of alpha-synucleinopathies." (PMID 34630068, 2021). "There was no visible colocalization of α-synuclein p-S129 and GFAP as well as Olig2, suggesting that α-synucleinopathy does not jeopardize astrocytes and oligodendrocytes in this mouse line." (PMID 34744697, 2021).